NGF (nerve growth factor)
Diseases named in the same sentence as NGF in open-access papers (continued):
Sharing a sentence is not in itself a finding about the gene and the disease.
corneal ulcer (18 papers, 2007 to 2025). Area of epithelial tissue loss from corneal surface; associated with inflammatory cells in the cornea and anterior chamber. "In the first published study about the application of NGF-eyedrops, severe corneal ulcers associated with anesthesia (corneal neurotrophic keratitis) were treated with purified mNGF." (PMID 23190582, 2012). "Supporting its therapeutic potential, a case report describing a 68-year-old HIV-positive male with an acyclovir-resistant herpetic corneal ulcer reported successful treatment with NGF eye drops." (PMID 40649793, 2025). "Nerve growth factor (NGF) has demonstrated great benefit in the treatment of neurotrophic corneal ulcers." (PMID 30599086, 2019). "The study revealed that the ocular discomfort lasted less than an hour after the instillation of eye drops and that any painful sensation disappeared, even when NGF treatments were continued after the healing of corneal ulcers." (PMID 23190582, 2012). "NGF eye-drops can promote the healing of corneal ulcers, and can be a therapeutic factor in preventig allograft rejection in the cornea." (PMID 22509106, 2012). "The case presented here is the first described in the literature in which a herpetic corneal ulcer was successfully treated with NGF." (PMID 17974026, 2007). "We evaluate the role of nerve growth factor (NGF) eye drops to treat a herpetic corneal ulcer resistant to systemic and local acyclovir treatment in an HIV-positive patient." (PMID 17974026, 2007). "In the study, four patients with severe corneal melting secondary to immune-related peripheral corneal ulcers received one drop of murine NGF solution (10 μg in 50 μL, equivalent to 200 μg/mL) every two hours (from 6 AM to 12 PM) for two days, followed by six times daily until the ulcer healed." (PMID 40649793, 2025). "Notably, Nerve Growth Factor (NGF) is recognized as a key player in corneal ulcer healing due to its role in epithelial regeneration and neural repair." (PMID 40519926, 2025). "The most recent research into NGF treatments has focused on neurotrophic keratitis, dry eye disease, optic neuropathy and optic pathway glioma, and the treatment of corneal ulcers of different etiologies, treated by topical NGF application in more than 200 patients, is of major interest." (PMID 34335170, 2021). "Another neurotrophic factor, NGF, stimulates the proliferation, migration, and differentiation of corneal epithelial cells in culture and has been shown to promote healing of corneal ulcers and impaired epithelial defects in several case studies and clinical trials." (PMID 32854428, 2020). "Indeed the majority of the in vitro and in vivo studies to date demonstrate that NGF exerts benefic effects in the treatment of major central neurodegenerative diseases, peripheral neuropathies, skin and corneal ulcers." (PMID 24244623, 2013). "Considering that nerve growth factor exerts beneficial effects in the treatment of major central and peripheral neurodegenerative diseases, skin and corneal ulcers, we asked whether nerve growth factor could also exert a role in Cyclosporine A-induced graft nephrotoxicity." (PMID 24244623, 2013). "Among them, recombinant human Nerve Growth Factor (NGF) eye drops, have been the focus of many developments in this field but have only been approved to treat corneal ulcers (Cenegermin OxervateTM)." (PMID 39076204, 2024). "Evidence shows that NGF is beneficial in wound healing in the cornea and DED, and NGF promotes healing of corneal ulcers." (PMID 36091713, 2022). "Experimental studies have recently demonstrated that nerve growth factor (NGF) is able to block HSV-1 reactivation and is also able to repair neurotrophic corneal ulcers." (PMID 17974026, 2007). "Moreover, recombinant human NGF (rhNGF) eye drops, such as Cenegermin (OxervateTM), have already been formulated and approved in the Unites States for the treatment of corneal ulcers, although they have not yet been approved in the European Union." (PMID 39076204, 2024).
oral cancer (18 papers, 2013 to 2025). "NGF blockade impairs the proliferation of oral cancer cells and relieves the general condition of murine oral cancer models." (PMID 40783715, 2025). "For oral cancer in animal models, anti-NGF mAbs impair the proper activation of NGF, decrease the volume of tumour lesions and relieve weight loss, accompanied by decreased levels of nociceptive receptors." (PMID 40783715, 2025). "Nerve growth factor (NGF) is a novel target of pain therapeutics for oral cancer, and it plays a main role in the nociception of chronic pain." (PMID 39099944, 2024). "NGF-targeted therapy presents a promising avenue for alleviating chronic pain, mitigating cachexia, and impeding tumor progression in patients with oral cancer." (PMID 39099944, 2024). "For instance, a higher expression of NGF in the oral cancer tissue than in the surrounding tissues was observed." (PMID 39906323, 2024). "It has been confirmed that NGF has a common link between pain, proliferation, and cachexia in oral cancer." (PMID 39099944, 2024). "Nerve growth factor (NGF) and adenosine triphosphate (ATP) are also secreted by oral cancer and can sensitize TRPV137,38." (PMID 35260737, 2022). "Similar results were also reported in an oral cancer pain model, where NGF was found to upregulate the expression of both TRPA1 and TRPV1." (PMID 35053150, 2021). "Nociceptive mediators produced and secreted by oral cancer include, but are not limited to, nerve growth factor, ATP, endothelin-1 and other proteases." (PMID 34572924, 2021). "Another study with a mouse cancer model simulating the anatomical and functional features found in human oral cancer patients demonstrated that anti-NGF treatment decreased plasma TNF-α and IL-6 levels." (PMID 35053150, 2021). "In oral cancer, neurotrophic factors (such as the nerve growth factor) have previously been suggested to regulate cancer/lesion progression, pain, and cachexia." (PMID 24155698, 2013). "A literature search revealed a positive correlation between NGF and oral cancer pain." (PMID 39099944, 2024). "In addition, other nociceptive mediators such as nerve growth factor (NGF) also promote nociception in mice bearing oral cancers." (PMID 33209112, 2020). "Anti-NGF could be a probable oral cancer mechanism-based therapy." (PMID 39099944, 2024). "NGF or TrkA blockade decreases tumor proliferation, invasion, metastasis, and PNI in oral cancer mice." (PMID 38324026, 2024).
atopic dermatitis (17 papers, 2009 to 2024). "Nerve growth factor (NGF) is implicated in chronic pain conditions by primary pain afferents and the level of NGF was confirmed to be increased in atopic dermatitis patients." (PMID 38400917, 2024). "In atopic dermatitis, NTs modulate the functional role of eosinophils as main target effector cells, and a significant correlation between NGF levels and the eosinophil major basic protein has been described in the eosinophils of affected patients." (PMID 38534776, 2024). "Treatment with PUVA for atopic dermatitis (AD) patients was able to minimize the over innervation of the epidermis and normalize the production of aberrant nerve growth factor (NGF) and signaling protein 3A (Sema3A) in the epidermis." (PMID 36627680, 2023). "This has been demonstrated for eosinophils by NGF being essential for tissue infiltration since NGF-neutralizing antibodies have been shown to reduce the number of eosinophils in the dermis and subcutis in allergic dermatitis in an animal model." (PMID 37047077, 2023). "Sema3A together with NGF acts as axon-guidance molecules in the skin in inflammatory skin disorders, such as atopic dermatitis." (PMID 36012289, 2022). "These fibers are engaged in the signaling of itch, and the serum levels of NGF are correlated with the clinical severity of atopic dermatitis." (PMID 35890193, 2022). "Several studies have confirmed increased levels of NGF or BDNF in atopic dermatitis, chronic spontaneous urticaria, symptomatic dermographism, acne vulgaris patients with depressive symptoms, and uremic patients with pruritus." (PMID 34620525, 2021). "It was reported that neuropeptides, especially substance P (SP) and calcitonin-gene-related peptide (CGRP), and neurotrophins such as nerve growth factor (NGF) affect the pathogenesis of skin disorders like atopic dermatitis and psoriasis vulgaris." (PMID 21977335, 2012). "Anti-NGF treatments can alleviate itching and allergic dermatitis." (PMID 39338343, 2024). "High levels of NGF have been found in the blood eosinophils of patients affected by atopic dermatitis, and in this group of patients, the eosinophil–NT interaction may be considered a potential cause of the onset and persistence of itching." (PMID 38534776, 2024). "In chronic prurigo, atopic dermatitis, and allergic contact dermatitis, NGF overexpression is accompanied by the hyperinnervation of skin nerves, which may cause itch or pain in the lesional skin." (PMID 35890193, 2022). "To test the functional relevance of mMCP4 upregulation we next used NGF and BDNF neutralizing antibodies, as this treatment has been shown to successfully neutralize neurogenic inflammation effects in allergic dermatitis." (PMID 38891925, 2024). "Mast cells and nerves often jointly regulate tissue inflammation and pathology; mast cells can secrete NGF and CADM1 is an important component of mast cell-nerve synapses that regulate the pathophysiology of atopic dermatitis lesions." (PMID 31052404, 2019).
prostatitis (16 papers, 2014 to 2025). An infectious or non-infectious inflammatory process affecting the prostate gland. "The overexpression of NGF in the bladder and urethra is associated with the modulation disability of micturition in the neurogenic bladder symptoms caused by SCI." (PMID 24884998, 2014). "This study demonstrated the important roles of the CXCL10/CXCR3, JAK/STAT3 and NGF/TrKA pathways in neuroinflammation and pain in chronic prostatitis, which provided novel therapeutic targets for pain management in chronic prostatitis." (PMID 39718951, 2025). "This highlights the importance of TRPV1 as a key target in prostatitis-induced bladder overactivity and as a necessary factor for NGF to drive bladder dysfunction." (PMID 39364048, 2024). "Three target genes proposed to be involved in the pathophysiology of bladder enlargement were studied, i.e., NGF and the two subtypes of angiotensin II receptor subtypes AT1 and AT2." (PMID 36891264, 2023). "Taken together, these findings demonstrated the important roles of the CXCL10/CXCR3 axis in modulating the JAK/STAT3 pathway and inducing neuroinflammation to mediate pain in chronic prostatitis, and targeting the NGF/TrKA pathway showed therapeutic efficacy in pain treatment in chronic prostatitis." (PMID 39718951, 2025). "Previous studies reported that several local immune mediators including NGF could bind to sensory neurons to mediate pain, hence, we explored the roles of the NGF/TrKA axis in pain responses in chronic prostatitis." (PMID 39718951, 2025). "The prostate NGF/TrKA axis was involved in the neuroinflammation and pain in chronic prostatitis, and inhibition of NGF could attenuate pain response in chronic prostatitis, which provided novel therapeutic targets for pain treatment in chronic prostatitis." (PMID 39718951, 2025). "One study discovered a correlation between prostatitis-induced bladder overactivity, alterations in TRPV1 in DRG, and heightened expression of neurogenic substances like NGF in the bladder mucosa with the heightened excitability of bladder afferent nerves triggered by prostatitis." (PMID 39364048, 2024). "NGF may play a role in urinary bladder dysfunction through promoting inflammation, as well as morphological and functional alterations in the sensory and sympathetic neurons that innervate the bladder." (PMID 35373950, 2022). "Here, we show that IL-6 and HGF, secreted by tumor neighboring visceral adipose stromal cells (V-ASCs), expand the metastatic colorectal (CR) cancer cell compartment (CD44v6 + ), which in turn secretes neurotrophins such as NGF and NT-3, and recruits adipose stem cells within tumor mass." (PMID 34408135, 2021). "Because mast cells release a number of inflammatory mediators such as NGF in injured tissues, we hypothesized that mast cell degranulation is involved in the nociceptive sensitization in this tibia fracture model of CRPS-I." (PMID 28594885, 2017). "NGF may also contribute to benign proliferation, as it has been observed in chronic prostate and chronic pelvic pain syndrome, since the abundance of NGF in prostate secretions varied in proportion to pain severity." (PMID 25187831, 2014). "In addition, increased nerve growth factor (NGF) in urine and tissue has been linked with bladder pathologies including idiopathic sensory urgency as well as BPS/IC." (PMID 24900993, 2014). "Moreover, the nerve growth factor (NGF)/TrKA axis was associated with the recruitment of spinal macrophages and pain development in chronic prostatitis, and inhibition of NGF decreased spinal macrophage recruitment and attenuated pain response in chronic prostatitis." (PMID 39718951, 2025). "Hence, the NGF may bind to the TrKA to activate the sensory neurons to mediate neuroinflammation and pain response in chronic prostatitis." (PMID 39718951, 2025).
prostatitis (continued). "Additionally, mast cells synthesize and release biologically active NGF in neuroimmune interactions, which was suppressed by Li-ESWT in a prostatitis rat model induced by intraprostatic injection of 1% carrageenan." (PMID 35563108, 2022).
COVID-19 (15 papers, 2020 to 2026). A disease caused by infection with severe acute respiratory syndrome coronavirus 2. "Probably the presence, at the time of sampling, of comorbidities associated with the COVID-19 pathology significantly influences the NGF and BDNF circulating levels." (PMID 39596862, 2024). "These pathways have been previously linked to COVID-19 severity and prognosis, with mitochondrial fatty acid beta oxidation, nerve growth factor, and hypoxia inducible factor showing particular relevance." (PMID 37949890, 2023). "It prevents loss of neural sensation in COVID-19 by stimulating the expression of neurotrophins like Nerve Growth Factor (NGF): Vitamin D: Induction of key neurotrophic factors." (PMID 36991346, 2023). "Whether the reduced level of NGF in milk from recovered COVID-19 mothers is associated with a lower population of lymphocytes remains to be evaluated." (PMID 33917718, 2021). "The association between COVID-19, neurotrophic factor reduction, and microglia activation emphasizes continuing research in exploring other therapeutic options aimed at moderating microglia overactivation, restoring NGF and BDNF presence, and decreasing inflammation." (PMID 39596862, 2024). "The authors revealed that in COVID-19 patients, NGF milk concentration was lower than that of unaffected donors, while BDNF levels were unchanged between groups." (PMID 39596862, 2024). "One of these studies showed decreased VGF (VGF nerve growth factor) expression in CSF from COVID-19 patients." (PMID 38002279, 2023). "We also investigated the ratios MMP-2/-9 vs. NGF/BDNF/NFL because it was proposed as a novel method to predict COVID-19 morbidity and mortality." (PMID 36831321, 2023). "Particularly, circulating and salivary levels of NGF increased in COVID-19 with respect to baseline (120.00 ± 70.00 pg/mL and 95.20 ± 25.60 pg/mL, respectively, in healthy controls)." (PMID 36579579, 2022). "The results of this study can be useful in prospecting assumptions for the transition from acute to chronic COVID-19, at least for NGF and BDNF, and alternative candidates for the prognosis of therapy." (PMID 36579579, 2022). "This study provides the first data on BDNF and NGF concentrations in human milk samples from mothers with a confirmed COVID-19 PCR test, mothers with previous viral symptoms suggestive of COVID-19, and unexposed mothers (control pre-pandemic 2018)." (PMID 33917718, 2021). "We demonstrated that NGF concentrations in human milk were lower in the COVID-19 PCR and viral symptoms groups than in the unexposed group, but BDNF was comparable." (PMID 33917718, 2021). "When the two outlier cases in the unexposed group for NGF were removed, NGF and cumulative NF levels were still higher in the unexposed group than in the COVID-19 PCR and viral symptoms groups (p < 0.05)." (PMID 33917718, 2021). "In summary, previous COVID-19 and mastitis infections changed differently the secretion of NGF and BDNF in human milk." (PMID 33917718, 2021). "Our study reveals that NGF concentrations in human milk were lower in mothers with a COVID-19 PCR test and mothers with viral symptoms suggesting COVID-19 than in unexposed mothers, but BDNF was comparable." (PMID 33917718, 2021). "NGF appears to reflect acute neuroimmune activation in COVID-19 and may serve as a dynamic biomarker of early inflammatory resolution." (PMID 41714345, 2026). "Other data have shown that the occurrence of new or more severe headaches due to COVID-19 elicited peripheral sensitization and microglial activation associated with serum changes in BDNF, TGF-ß1, VEGF, NGF, and CX3CL1 suggestive of long-lasting severe inflammation or immune dysregulation." (PMID 39596862, 2024). "Previous studies debated the role of NGF in pulmonary pathologies, alluding to the possibility of considering the NGF signaling as a potential diagnostic/therapeutic target in SARS-CoV-2-induced pulmonary complications, contributing to the antibody production in convalescent COVID-19." (PMID 36831321, 2023).